MT1E (metallothionein 1E)
Description:
Metallothioneins have a high content of cysteine residues that bind various heavy metals; these proteins are transcriptionally regulated by both heavy metals and glucocorticoids.
Synonyms: MT-1E; MT-IE; MTD; MT1
Tractability: PROTAC: ubiquitination databases record sites on it.
Gene: Protein-coding gene on chromosome 16 (56,625,475 to 56,627,112, forward strand). Ensembl gene ENSG00000169715.
Subcellular location (Human Protein Atlas): Nucleoplasm
Pathways (Reactome):
Cellular responses to stimuli: Metallothioneins bind metals
Gene Ontology:
Molecular function: protein binding; metal ion binding; zinc ion binding
Biological process: cellular response to cadmium ion; cellular response to zinc ion; cellular response to copper ion; detoxification of copper ion; intracellular zinc ion homeostasis; negative regulation of growth
Cellular component: cytoplasm; nucleus
Genetic constraint (gnomAD): Loss-of-function variants: 2 observed, 3.52 expected, observed/expected ratio (o/e) 0.57, 90% interval 0.23 to 1.62. That is too few expected variants to judge how well the gene tolerates losing a copy. Missense variants: 145 observed, 152.99 expected, observed/expected ratio (o/e) 0.95, 90% interval 0.83 to 1.09. Synonymous variants: 78 observed, 65.25 expected, observed/expected ratio (o/e) 1.2, 90% interval 1 to 1.44.
Homologues: Orthologues: chimpanzee MT1E (97% identical), chimpanzee MT1M (53% identical), zebrafish mt2 (19% identical). Paralogues in human: MT1A (28% identical), MT1F (28% identical), MT2A (27% identical), MT1G (26% identical), MT1B (25% identical), MT1H (25% identical), MT1HL1 (25% identical), MT1X (24% identical), MT1M (23% identical), MT3 (21% identical), MT4 (16% identical).